TNF (tumor necrosis factor)
Diseases named in the same sentence as TNF in open-access papers (continued):
Sharing a sentence is not in itself a finding about the gene and the disease.
epilepsy (continued). "What's more, the dysregulation of TNF and IER3 pathways in PM‐associated epilepsy suggests therapeutic potential for targeted immunomodulation (e.g., TNF signaling blockade), which may mitigate seizure susceptibility in high‐risk patients." (PMID 41466027, 2026). "Given that excessive production of TNF‐α, IL‐6, and IL‐1β has been implicated in neurodegenerative diseases and epilepsy, our findings suggest that Listerin may serve as a protective factor against pathological neuroinflammation." (PMID 40448625, 2025). "The release of proinflammatory cytokines (IL-1β, IL-6, and TNFα) can lead to neuroinflammation and disruption of the blood–brain barrier, which are associated with increased seizure susceptibility and the development of epilepsy." (PMID 38612542, 2024). "TNF‐α is associated with epilepsy pathogenesis and correlated with seizure recurrence." (PMID 38361811, 2024). "The IL-1 receptor/TLR signaling, cyclooxygenase-2, tumor necrosis factor-alpha, complement signaling, and chemokines are also implicated in epilepsy and could be potential therapeutic targets." (PMID 38612542, 2024). "Tumor Necrosis Factor Alpha (TNF-α) is an inflammatory cytokine associated with epilepsy." (PMID 37981693, 2023). "Studies have shown that TNF-α can cause the activation of microglia cells and accelerate the death of peripheral neurons, which plays an important role in the occurrence and progression of epilepsy." (PMID 38074156, 2023). "TNF, a pro-inflammatory cytokine, has previously been linked to epilepsy." (PMID 35598439, 2022). "However, intermittent reduction or loss of neuronal excitatory input after TBI can induce production of TNFα by reactive astrocytes, and overexpression of TNFα is associated with the development of epilepsy." (PMID 36619916, 2022). "Furthermore, TNF-α and IL-1β are found to be increased in the kainic acid-induced epilepsy model, and seizure susceptibility correlates with microglia development in the hippocampus." (PMID 34948222, 2021). "Exacerbated inflammation could be a consequence as well as a cause of epilepsy, and several inflammatory mediators, such as IL1β, TNF, and IL6, have been detected in surgically resected brain tissue from epileptic patients." (PMID 33407600, 2021). "In preclinical researches, certain ligands of TNF receptor have come to exploring as underlying treatment targets in epilepsy, while it is still under controversy whether the therapeutics against epilepsy targeting TNF-α signaling may generate the serious risks of infection and tumorigenesis." (PMID 38187384, 2023). "Taken together our data are consistent with a model in which TNF-α causes premature stabilization of developing synapses within the tectum, therefore preventing normal refinement and synapse elimination that occurs during development, leading to increased local connectivity and epilepsy." (PMID 20067608, 2010). "Quantitative PCR revealed that IL-1β, IL-6, and TNF-α mRNA levels were markedly elevated in the PBS-treated epilepsy group but significantly suppressed in the L. eligens-treated epilepsy group." (PMID 41356796, 2026). "The differential expression of four DE‐SRGs between control and epilepsy groups, including IER3, TNF, GPANK1 (upregulated), and ATF6B (downregulated), further elucidates the molecular mechanisms underlying the epilepsy phenotype." (PMID 41466027, 2026). "Evidence suggests that it exerts antiepileptic effects by lowering proinflammatory cytokine levels such as TNF-α in animals with kainic acid-induced epilepsy." (PMID 41328216, 2025). "In our study, we observed a marked increase in the expression levels of key inflammatory markers, specifically NFκB, IL‐1β, and TNF, in rats diagnosed with epilepsy." (PMID 41523603, 2025). "in the prevention and treatment of epilepsy, as manifested in its regulation of the Circ_Csnk1g3/Csnk1g3-85aa/ CK1γ3/TNF-α pathway to inhibit hippocampal neuronal necroptosis and inflammation." (PMID 39920301, 2025).
epilepsy (continued). "The serum levels of TNF-α in patients with epilepsy are higher than those in healthy people and are positively correlated with the severity of epilepsy." (PMID 39858450, 2025). "In patient brain tissue and epilepsy models, upregulation of TNF-α expression often coexists with epileptic activity and neuronal injury." (PMID 41306289, 2025). "show some seizure-reducing effects in animal models of epilepsy, but their direct clinical application remains controversial due to the wide range of biological roles and potential side effects of TNF-α." (PMID 41306289, 2025). "The proinflammatory cytokine TNF is rapidly released by reactive microglia and exerts proepileptic effects in experimental epilepsy via TNF receptor 1 (TNFR1) signaling." (PMID 39607395, 2025). "In epilepsy, TNF-α boosts brain activity by increasing α-amino-3-hydroxy-5-methyl-4-isoxazolepropionic acid (AMPA) receptors at synapses, which play a role in seizure development." (PMID 40941042, 2025). "TNF-α is a classical pro-inflammatory factor secreted by macrophages, microglia, and is equally important in epilepsy pathology." (PMID 41306289, 2025). "Previous studies in epilepsy patients treated with VNS have shown that incubating whole blood with endotoxin results in a significantly reduced release of TNF‐α, IL‐1β, and IL‐6 4 h post‐VNS." (PMID 39903575, 2025). "Compared with CBZ use, VPA use led to lower levels of IL-2, IL-8, and TNF-α in 120 epilepsy patients, including 60 VPA- and 60 CBZ-treated patients, which is similar to our findings." (PMID 40806813, 2025). "Among these, TNF‐α, IL‐1β levels and its receptor IL‐1R1 in human serum have been suggested to correlate with the severity of epilepsy." (PMID 39907034, 2025). "The administration of therapeutic levetiracetam doses decreased serum IL-1β level in patients with different types of epilepsies as well as serum IL-1β and TNF-α level in healthy female subjects." (PMID 40431461, 2025). "Compared to the healthy volunteers, epilepsy patients had significantly increased serum levels of the inflammatory factors IL-6, IL-1β, TNF-α, and CRP (P < 0.05), while SIRT3 levels were significantly decreased." (PMID 39091611, 2024). "Hidradenitis suppurativa (HS) is the main pathology of cognitive and functional disorders mainly related to epilepsy, primarily temporal epilepsy, with the release of IL-1b, TNF, and IL-6." (PMID 39166055, 2024). "As a result, our further screening demonstrated that pro-inflammatory cytokines (PICs), such as IL-1β, IL-6, and TNF-α, and the TLR4/NF-κB pathway were associated with APS' effects in treating epilepsy." (PMID 38405667, 2024). "Increased pro‐inflammatory cytokines including tumor necrosis factor‐alpha (TNF‐α), IL‐1β, and IL‐6 were also observed in an epilepsy mouse model with Gabrg2+/Q390X knockin, indicating neuroinflammation was one of the mechanisms for genetic epilepsy." (PMID 38357846, 2024). "Extensive research has confirmed that excessive activation of astrocytes and the subsequent release of various pro-inflammatory cytokines, such as IL-1β, IL-6 and TNF-α, are considerably involved in the pathogenesis and progression of epilepsy." (PMID 39598325, 2024). "The elevation of inflammatory mediators, including IL-1β, TNF-α, and IL-6, was initiated 2 h following seizures and increased to the highest concentration between 6 and 12 h following seizures in the epilepsy mouse model." (PMID 39723425, 2024). "To ascertain the involvement of neuroinflammation in the therapeutic mechanism of Gent-treated epilepsy seizures in mice, we conducted an evaluation of the protein levels of IL-1β, TNF-α, and IL-6 in hippocampi using Western blot analysis." (PMID 39598325, 2024). "Consistent with our findings, liraglutide reduced IL-1β and TNF-α levels in a rat model of PTZ-induced epilepsy, highlighting the NLRP3 inflammasome complex as a potential target for antiepileptogenic treatments." (PMID 39457518, 2024).
epilepsy (continued). "In the study, IL‐1β, TNF‐α, and Iba‐1 levels were found to be high in KA‐induced epilepsy, whereas overexpression of circHivep2 dramatically decreased the elevated levels of IL‐1β and TNF‐α." (PMID 38676299, 2024). "At 72 h following KA‐induced epilepsy, circHivep2+ exosomes further reduced the levels of pro‐inflammatory cytokines, IL‐1β, cytokine release, and TNF‐α in the hippocampus." (PMID 38676299, 2024). "Chronic neuroinflammation can contribute to epilepsy through mechanisms such as elevated TNF-α expression, promoting hyperexcitability and the activation of AP-1, which regulates apoptosis through pathways including JNK signaling." (PMID 37239256, 2023). "In this study, we found that levels of TNF-α and IL-1β were significantly higher than those in the control group, indicating that TNF-α and IL-1β played a vital role in the pathogenesis of epilepsy." (PMID 38077432, 2023). "Activated microglia have been shown to be the primary source of TNF-α in the mouse model of epilepsy used in the current study." (PMID 36862288, 2023). "In a study, diclofenac decreased IL‐1β and TNF‐α values in brain homogenates in the kindling epilepsy model created with pentylenetetrazol." (PMID 37688418, 2023). "KEGG pathway analysis results showed that hippocampal inflammatory pathways were significantly activated after PTZ kindled epilepsy, such as the cytokine receptor interaction, TNF signaling pathway, Jak-STAT signaling pathway, and NF-κB signaling pathway." (PMID 36985783, 2023). "After seizures, patients with epilepsy were observed to have elevated serum and cerebrospinal fluid TNF-α, IL-1β, IL-6, and IL-1 receptor antagonist levels." (PMID 37239256, 2023). "In clinical studies, an increase in the content of proinflammatory cytokines IL-1β, interleukin-6 (IL-6), and tumor necrosis factor-α (TNF-α) was found in the cerebrospinal fluid of patients with epilepsy after an epileptic seizure." (PMID 37047481, 2023). "ROS and inflammatory factors, primarily TNF-α and IL-6, result in nervous system insults via induction of inflammation and ER stress in brain tissues, which subsequently increase the risks of epilepsy." (PMID 38074156, 2023). "TNF-α is among the most extensively investigated proteins in the studies on inflammatory mediators in human epilepsy." (PMID 36142325, 2022). "By regulating miR-203, UCA1 decreases IL-1β, IL-6, TNF-α, and Cox-2 levels via miR-499b-5p in epilepsy." (PMID 35898503, 2022). "The release of proinflammatory cytokines such as interferon-α (IFN-α), tumor necrosis factor-α (TNF-α), IL-6, and IL-1β are pivotal players in epilepsy and psychiatric disorders." (PMID 35712347, 2022). "The elevation of inflammatory cytokines, such as tumor necrosis factor and interleukin, were also detected in patients with epilepsy and in epilepsy models." (PMID 35528742, 2022). "Our results suggest that children with drug-resistant epilepsy are more likely to benefit from KD treatment when specific Bifidobacteria and TNF are elevated." (PMID 35598439, 2022). "Noteworthy, the blockade of Kv1.3 attenuated KA-induced epilepsy and inhibited microglial activation and the release of proinflammatory cytokines (such as IL-1β, IL-6, and TNF-α) through the Ca2+/NF-κB signaling pathway." (PMID 36499018, 2022). "Meanwhile, NEAT1 promotes IL-6, cyclooxygenase (COX)-2, and TNF-α expression by targeting miR-129-5p and activating the Notch signaling pathway in epilepsy." (PMID 35898503, 2022). "Tumor necrosis factor alpha (TNF-α), a pro-inflammatory cytokine primarily released from microglia, has recently reported to be involved in the etiology of epilepsy and attenuate aberrant neurogenesis." (PMID 35898503, 2022). "During epilepsy, inflammatory activation of glial cells leads to the production of interleukin-1-beta, interleukin-6, and TNF-α, which are able to perpetuate inflammation to other neurons and recruit adaptive immune response cells in the brain." (PMID 36138769, 2022).
epilepsy (continued). "The content of TNF-α was positively correlated with the severity of epilepsy, which was higher in the severe epilepsy group than in the mild group, while the nonepileptic group is at a minimum level." (PMID 33959658, 2021). "HDAC5 silencing or miR-485 mimic reduced the formation of IL-1β, TNF-α, and IL-6 by epilepsy model neurons, and this effect was rescued by HDAC5 overexpression." (PMID 34021541, 2021). "The level of IL-1β and TNF-α in the VPA-resistant group was substantially higher than that in children with VPA-sensitive epilepsy." (PMID 34497517, 2021). "This indicates that the TNFα signal can lead to an increase in the purinergic signal of astrocytes, thereby inducing epilepsy." (PMID 35069411, 2021). "For instance, IL-1β, IL-6, IL-10, IL-2, IL-17, IL-4, and TNF-α were abnormally expressed in patients, whose elevated levels can lead to neuronal degeneration and induce epilepsy." (PMID 33746751, 2021). "LncRNA NEAT1 promoted IL-6, COX-2, and TNF-α expression by targeting miR-129-5p and activating the Notch signaling pathway in epilepsy." (PMID 33776905, 2021). "The increase in acetylcholinesterases was related to an increase in inflammatory cytokines (IL-1β, IL-12, and TNFα), activation of microglia, and development of epilepsy." (PMID 34948222, 2021). "Through proteomics analysis, we identified that HIF-1α was overexpressed in mice with VPA-resistant epilepsy, and regulated the expression of interleukin-1β and tumor necrosis factor-α." (PMID 34497517, 2021). "The most commonly studied IL-1β, IL-6, and TNF-α tend to be potential mediators in the neuropathology of epilepsy." (PMID 34976232, 2021). "The levels of several pro-inflammatory cytokines such as IL-1β, IL-6, and TNF-α are often elevated in cerebrospinal fluid and serum of patients or rats with epilepsy." (PMID 34924959, 2021). "Thirdly, this study found the dysregulation of miR-221-3p, IL-1β, and TNF-α in VPA-resistant epilepsy, and confirmed the influence of these mediators on seizure severity." (PMID 34497517, 2021). "In line with the role ofinflammatory agents in epilepsy, the induction of IL1α, TNF-α, and IL-6 has been shown in both neuronsand glia before epilepsy onset." (PMID 33650824, 2021). "Gene expression profiling of hyperexcitable brain tissue resected from patients with epilepsy also revealed a remarkably similar pathology to that seen in the brains of colitic mice, including neutrophil infiltration and high TNFα expression." (PMID 34511110, 2021). "An in vitro study suggested that after epilepsy, IL-1β mRNA, IL-6 mRNA, and TNF-α mRNA were expressed by microglia and astrocyte." (PMID 34976232, 2021). "Above results evidence that upregulation of HIF-1α expression in VPA-resistant epilepsy leads to increased expression of IL-1β and TNF-α." (PMID 34497517, 2021). "A previous study employing kindling model of epilepsy has reported a correlation between TNF-α and epileptogenesis, where TNF-α administered rats exhibited prolonged seizure." (PMID 33920713, 2021). "Low-dose TNF-α (5.0 μg/kg) significantly increased the frequency of epilepsy and prolonged the duration of neuronal firing." (PMID 33959658, 2021). "Western blotting in mice hippocampal tissue was carried out, and results indicated that expression of HIF-1α, IL-1β, and TNF-α in the hippocampus of mice with VPA-resistant epilepsy was upregulated compared with that in mice with VPA-sensitive epilepsy." (PMID 34497517, 2021). "Since this study focused on the role of HIF-1α in VPA-resistant epilepsy, we prioritized IL-1β and TNF-α that directly interact with HIF-1α." (PMID 34497517, 2021). "Proteomics analysis revealed that overexpressed HIF-1α interacted with IL-1β and TNF-α in mice with VPA-resistant epilepsy, which was also confirmed by western blotting." (PMID 34497517, 2021).
epilepsy (continued). "The levels of pro‐inflammatory cytokines, TNF‐α and IL‐1β, and cytokine release were further decreased by circHivep2+ exosomes in the hippocampus at 72 hours after KA‐induced epilepsy." (PMID 33002329, 2020). "In the present study, we found that levels of Iba‐1, TNF‐α and IL‐1β were increased in KA‐induced epilepsy but overexpression of circHivep2 significantly reduced the elevated levels of TNF‐α and IL‐1β." (PMID 33002329, 2020). "Serum α-synuclein did not showed significant correlation with serum levels of IFN-β, IFN-γ, IL-1β, IL-6, IL-10 and TNF-α in patients with epilepsy and acquired demyelinating disorders of the CNS." (PMID 32151248, 2020). "The most studied cytokines regarding astrogliosis and epilepsy are interleukin-1 beta (IL-1β), IL-6, and tumor necrosis factor-alpha (TNF-α); pro-inflammatory cytokines that can be released by reactive astrocytes and activated microglia." (PMID 33324329, 2020). "In the clinic, in a small cohort study of patients with neonatal HI, elevated IL-6, TNFα, and IL-1β were found to be associated with the subsequent onset of epilepsy, suggesting that these cytokines may hold value as predictive biomarkers of later life epilepsy risk." (PMID 32116690, 2020). "Numerous studies have shown upregulation of IL-1β, IL-6, and TNF-α in animals with (recurrent) seizures and patients with epilepsy." (PMID 33324329, 2020). "Earlier findings reported upregulated level of TNF-α in epilepsy either in rodents or in adult zebrafish." (PMID 32260203, 2020). "Both clinical and preclinical studies have indicated that proinflammatory cytokines, including IFNγ and TNFα, play important roles in the development of epilepsy and several neuropsychiatric disorders." (PMID 31366130, 2019). "In our research, we found that the protein expression of pro-inflammatory factors, including TNF-α, IL-1β, IL-6, and IL-10, was higher in pilocarpine-induced epilepsy." (PMID 31231220, 2019). "Specifically, proinflammatory cytokines, tumor necrosis factor α (TNFα), and interferon γ (IFNγ) probably contribute to development of epilepsy (epileptogenesis, ictogenesis, and seizure-related brain damages), and several neuropsychiatric disorders." (PMID 31366130, 2019). "In particular, high levels of proinflammatory cytokine (IL-1β and TNF-α) are found in epileptogenic tissues from mice with epilepsy of various etiologies." (PMID 30922332, 2019). "In the pilocarpine model of epilepsy, proinflammatory cytokines in the blood of omega-3 fatty acid-treated rats, including IL-1ß, TNF-α, and IL-6,all decreased, supporting the anti-inflammatory role of n-3 PUFAs in epilepsy." (PMID 31185666, 2019). "We found that FK506 not only had direct neuroprotective effects but also inhibited the expression of inflammatory factors VCAM-1, ICAM-1, PKCδ, and TNF-α after seizures, thereby indirectly inhibiting the development of epilepsy." (PMID 31572289, 2019). "Compared with the control group, PKCδ and TNF-α were significantly increased in the acute phase (6 h) but gradually decreased in the later stage of SE in the epilepsy group." (PMID 31572289, 2019). "In the central nervous system, interleukin (IL)‐1β, IL‐6 and tumour necrosis factor (TNF)‐α have a regulatory role in pathophysiological processes of epilepsy." (PMID 31144434, 2019). "It was reported that the levels of inflammatory cytokines including tumor necrosis factor alpha, interleukin-6, and interleukin-1 beta as well as interleukin-1 receptor antagonist significantly increased in patients with epilepsy." (PMID 32341973, 2019). "The “Epilepsy-only” patients had significantly higher serum and mRNA levels of IL-1α, β, IL-2,6,8, and TNF-α compared to the controls and the “Cannabis+Epilepsy” group (p = 0.0001)." (PMID 31757102, 2019). "Collectively, TRPV1 promoted astrocyte migration thus helped the infiltration of pro-inflammatory cytokines (TNF, IL-1β, IL-6, and iNOS) from astrocytes into the vicinity of neurons to promote epilepsy." (PMID 31722723, 2019).